GLT6D1 (glycosyltransferase 6 domain containing 1)
Synonyms: GLTDC1; GT6M7
Tractability: Antibody: UniProt predicts a signal peptide or a membrane-spanning region.
Gene: Protein-coding gene on chromosome 9 (135,623,648 to 135,641,216, reverse strand). Ensembl gene ENSG00000204007.
Subcellular location: Membrane
Gene Ontology:
Molecular function: glycosyltransferase activity; hexosyltransferase activity
Biological process: carbohydrate metabolic process
Cellular component: Golgi apparatus; vesicle; membrane
Genetic constraint (gnomAD): Loss-of-function variants: 3 observed, 5.6 expected, observed/expected ratio (o/e) 0.54, 90% interval 0.24 to 1.36. That is too few expected variants to judge how well the gene tolerates losing a copy. Missense variants: 300 observed, 307.67 expected, observed/expected ratio (o/e) 0.98, 90% interval 0.89 to 1.07. Synonymous variants: 117 observed, 122.35 expected, observed/expected ratio (o/e) 0.96, 90% interval 0.82 to 1.12.
Homologues: Orthologues: macaque GLT6D1 (89% identical), chimpanzee GLT6D1 (84% identical), dog GLT6D1 (66% identical), pig GLT6D1 (64% identical), mouse Glt6d1 (63% identical), rat Glt6d1 (62% identical), guinea pig GLT6D1 (57% identical). Paralogues in human: A3GALT2 (35% identical), GBGT1 (34% identical), ABO (32% identical).
Diseases named in the same sentence as GLT6D1 in open-access papers:
GLT6D1 is named in the same sentence as 3 diseases in open-access papers, as found by Europe PMC text mining. Sharing a sentence is not in itself a finding about the gene and the disease. The quoted sentences say what the papers report.
periodontitis (5 papers, 2012 to 2022). An acute or chronic inflammatory process that affects the tissues that surround and support the teeth. "This study identified an association with a marker in the locus of GLT6D1 and functional experiments suggested that reduced GATA3 binding affinity to the GLT6D1 locus could be a component of the pathophysiology of periodontitis." (PMID 25008200, 2014). "Whether GLT6D1 encodes a functional glycosyltransferase or not remains to be determined, however, a genome-wide association study (GWAS) has associated polymorphic markers of single nucleotide polymorphism (SNP) at this genetic locus to the periodontitis susceptibility." (PMID 28839219, 2017).
GLT6D1 also shares sentences with these, for which no sentence is quoted: diabetes (1 paper); periodontal disease (1).